IQCF2 (IQ motif containing F2)
Tractability: No criterion of Open Targets' tractability assessment is met for any kind of drug.
Gene: Protein-coding gene on chromosome 3 (51,861,615 to 51,863,424, forward strand). Ensembl gene ENSG00000184345.
Gene Ontology:
Molecular function: protein binding; calmodulin binding
Cellular component: acrosomal vesicle
Genetic constraint (gnomAD): Loss-of-function variants: 10 observed, 13.9 expected, observed/expected ratio (o/e) 0.72, 90% interval 0.44 to 1.22. The upper end of that interval is the gene's LOEUF score, 1.22, which puts it in group 5 of 6, group 1 being the genes least tolerant of losing a copy. Missense variants: 171 observed, 209.1 expected, observed/expected ratio (o/e) 0.82, 90% interval 0.72 to 0.93. Synonymous variants: 66 observed, 75.25 expected, observed/expected ratio (o/e) 0.88, 90% interval 0.72 to 1.08.
Homologues: Orthologues: chimpanzee IQCF2 (99% identical), macaque IQCF2 (91% identical), pig IQCF2 (77% identical), dog IQCF2 (72% identical), rabbit IQCF2 (71% identical). Paralogues in human: IQCF1 (44% identical), IQCF5 (40% identical), IQCF6 (40% identical), IQCF3 (39% identical).